TLR9 (toll like receptor 9)
Diseases named in the same sentence as TLR9 in open-access papers (continued):
Sharing a sentence is not in itself a finding about the gene and the disease.
infection (continued). "We had expected that TLR9 would contribute to host recognition of S. aureus in the craniotomy infection model based on the presence of bacterial extracellular DNA (eDNA) in the biofilm matrix." (PMID 32290861, 2020). "Since TLR9 expression is mainly manifested at 24 h post infection, it is possible that HSV-2 drives a response which subsequently activates TLR9 promoter." (PMID 32194565, 2020). "The third section describes the role of TLR9 in recognizing self-DNA in the endolysosomes during infections depending on the self-DNA characteristics and various inflammatory diseases." (PMID 33643304, 2020). "Time-course assay revealed that HSV-2 induced TLR9 promoter activation in an infection time-dependent manner, which peaked around 24 h after infection." (PMID 32194565, 2020). "Following infection, the levels of TLR9 mRNA in the lungs of klotho WT and KO mice increased at 1 day post-infection and subsequently decreased at 3 days post-infection." (PMID 33329595, 2020). "Activation of TLR9 in this early window of disease would ideally result in improved viral combat thereby preventing or shortening of symptomatic infection and prevention of overwhelming viral illness and tissue damaging inflammation." (PMID 33519463, 2020). "The use of CPG as an adjuvant in vaccines is a strategy widely used against some models of infection, as it has great potential to induce and increase Th1 type immune response through TLR9 activation." (PMID 33194839, 2020). "It has been demonstrated that infection by certain DNA viruses activates the TLR9 signaling pathway, in which TLR9 interacts with myeloid differentiation factor 88 (MyD88)." (PMID 32714322, 2020). "Taken together, our results suggest that following HIV exposure in Chinese HESN individuals, the increased level of TLR9 expression was associated with enhanced innate immune responses, which, in turn, interfere with HIV replication and productive infection." (PMID 32547554, 2020). "Human mitochondrial DNA (mtDNA), evolutionary derived from endosymbiont bacteria, contains unmethylated CpG-motifs and is an example of a well-known DAMP that triggers inflammatory responses directly via TLR9 during injury and/or infection." (PMID 33519463, 2020). "Further infection dose assay showed that TLR9 promoter activation was enhanced when HSV-2 dose increased." (PMID 32194565, 2020). "Wild type (WT), TLR2 knockout (KO), TLR9 KO, and caspase-1 KO mice were examined at various intervals post-infection to quantify bacterial burden, leukocyte recruitment, and inflammatory mediator production in the galea, brain, and bone flap." (PMID 32290861, 2020). "Endosomal DNA-sensor Toll-like receptor (TLR)-9 has been shown to recognize microbial DNA and induces the host defense against infections, such as Human cytomegalovirus (HCMV), Herpes simplex virus (HSV)-1 and HSV-2." (PMID 32140147, 2020). "TLR9 and FoxP3 were up-regulated in dog skin at the early stages of infection and in lymph nodes and significant downregulation of TLR3, TLR4, TLR9, IL-17, IL-22, and FoxP3 transcription was found associated with disease progression." (PMID 33352885, 2020). "Higher TLR-7 levels were found in infection patients than in the gout and HC groups (0.46 vs 0.28 vs 0.30 ng/ng B2M, p<0.05), whereas lower TLR-9 levels were found in sepsis than infection and HC groups (0.015 vs 0.034 vs 0.025 ng/ng B2M, p<0.05)." (PMID 30890150, 2019). "We also evaluated the infection of dendritic cells by Leishmania amazonensis, however, it was not possible to observe the activation of infected dendritic cells in WT and TLR9-/-." (PMID 30802247, 2019). "These DNA fragments, that contain CpG sequences, activate TLR9, thereby developing a protective immune response against infection." (PMID 30802247, 2019). "In the peak of infection, vaccinated TLR9-/- mice partially controlled the lesion in comparison with control TLR9-/- mice injected with PBS." (PMID 30802247, 2019).
infection (continued). "TLR3, TLR7, and TLR9 are known to be important host factors involved in restricting EV71 infection in diverse infection models in vivo and in vitro." (PMID 31730654, 2019). "Toll-like receptors, such as TLR2, TLR3, TLR7, and TLR9 have been described to mediate antiviral activities against HSVs during infection." (PMID 31114761, 2019). "In previous work, adenovirus was shown to activate the NLRP3 inflammasome at early time points of infection through TLR9 sensing the virus double-stranded DNA after endosomal membrane penetration." (PMID 31849970, 2019). "To understand if TLR9-/- mice were susceptible to a single MRSA infection, we monitored mice for 7 days post-infection." (PMID 30682165, 2019). "In both experiments we noted that the TLR9-/- mice appeared healthier than did the WT mice in terms of posture, grooming and activity in the cage post-dual infection." (PMID 30682165, 2019). "The dichotomous role of TLR9, promoting or suppressing the infection, depends on the gastric environment." (PMID 30863783, 2019). "Cellular recognition of CpG motifs occurs via Toll-like receptor 9 (TLR9), which normally activates immune responses to pathogen-associated molecular patterns (PAMPs) indicative of infection." (PMID 31508424, 2019). "Using light microscopy, the infection of WT macrophages and TLR9-/- macrophages was evaluated, and a similar infection profile was observed between both groups." (PMID 30802247, 2019). "We also detected TLR9 mRNA increased 24 hours post-PR8 infection in cultured bone marrow derived macrophages (BMDMs)." (PMID 30682165, 2019). "The signal to mediate this increase was likely independent of IAV recognition by TLR7, or by IAV-induced release of CpG rich mitochondrial (mt)DNA as TLR7 and TLR9 agonist stimulation lead to downregulation of TLR9 gene expression relative to mock infection." (PMID 30682165, 2019). "To our knowledge, we are the first to report that infection of macrophages ex vivo with IAV can increase TLR9 expression." (PMID 30682165, 2019). "In another set of experiments, mice lesions were monitored until the peak of infection (67 dpi), confirming the higher lesion size in infected TLR9-/- mice." (PMID 30802247, 2019). "Protein expression was also increased in these lung leukocytes post-PR8 infection as measured by TLR9 immunoblotting." (PMID 30682165, 2019). "TLR9 1635A/G polymorphism has also been previously studied in context of HIV infection and associates with HIV acquisition/infection, disease progression, CD4 counts and viral load." (PMID 30651082, 2019). "TLR4 haplotype GCAG [p = 0.0035, OR = 0.44 (0.20–0.96)] was associated with the decreased risk whereas TLR9 haplotype GATC [p = 0.018, OR = 4.15 (1.16–14.80)] was associated with the increased risk of acquiring HPV 16 and 18 infection compared with controls." (PMID 31278284, 2019). "The parasite loads at 52 dpi suggest that the LaAg vaccine efficacy is partially dependent on TLR9 activation in the peak of infection." (PMID 30802247, 2019). "TLR2 KO mice showed modest mortality with 30, 30, and 40%, while TLR9 KO mice exhibited apparently enhanced mortality with 55, 60, and 70%, depending on the infection dose." (PMID 29760708, 2018). "Supporting this idea, a recent report described how TLR9 negatively regulates the NLRP3–IL-1β pathway in an infection model." (PMID 29774028, 2018). "We found that after infection with a low dose (3 × 103 PFU per mouse) of ECTV, mice deficient in Tlr9 (Tlr9−/−) or Sting (Stinggt/gt) were highly susceptible to mousepox." (PMID 29963044, 2018). "UNC93B1 can facilitate trans-location of TLR (TLR3, TLR7 and TLR9) from the endoplasmic reticulum to the Golgi and mediates the host immune responses to infection with murine cytomegalovirus, as well as several intracellular protozoan parasites." (PMID 29530077, 2018).
infection (continued). "The results illustrated that TLR2, TLR4 and TLR9 were up-regulated by over 300% in HEC-1-A cell 24 h post-infection (p.i.), and only TLR4 transcription was enhanced by over 700% in VK2 cells." (PMID 30419930, 2018). "While TLR2 and TLR4 play no role controlling B. abortus infection in mice, TLR9 correlated to restricting infection, and recently TLR9 was shown to be activated by B. abortus DNA-derived CpG motifs." (PMID 30589883, 2018). "Then, we tested the in vivo cytotoxicity against TSKB20-loaded target cells both in B6 and Tlr9−/− vaccinated mice at an early time point (day 8 pi) after the challenging infection." (PMID 29896197, 2018). "Infection of JAWS II cells led to 4.11 ± 1.23 higher level of TLR9 mRNA in comparison to uninfected control cells (p = 0.039)." (PMID 29872440, 2018). "TLR9−/− neutrophils presented a normal activation profile during infection, while TLR2−/− neutrophils presented a defective effect on the expression of CD11b, an integrin expressed on the surface of neutrophils." (PMID 28280488, 2017). "Studies showed that treatment with TLR4 and TLR9 agonists decreased the disease severity following challenge infection with L. major in BALB/c mice." (PMID 29312309, 2017). "The C/T (TLR5 R392StopCodon) and T/T (TLR9 -1486C/T) genotypes appear to be risk factors for infection by P. vivax (TLR5: C/C vs. C/T [OR: 2.116, 95% CI: 1.054–4.452, p = 0.031]; TLR9: C/C vs. T/T [OR: 1.919, 95% CI: 1.159–3.177, p = 0.010]; respectively)." (PMID 28850598, 2017). "Another research reported before that the GA heterozygotic status in the analyzed TLR9 SNP, carried by fetuses and neonates, congenitally infected with HCMV, had significantly increased the risk of the infection." (PMID 28340580, 2017). "In this study, we found a significant and consistent increase in TLR2, TLR4, and TLR9 transcripts in the brains of lethally infected mice at days 6 and 10, as well as in brains of sublethal infection." (PMID 28742087, 2017). "On the other hand, lack of TLR9 signaling significantly attenuated the secretion of IL-1β following IOE infection in TLR9-/- BMM, and abrogated S6 phosphorylation." (PMID 29049365, 2017). "Here, we observed that infection with L. braziliensis leads to a higher expression of TLR9, when compared with L. infantum strains." (PMID 29358935, 2017). "Rational for this disparity is that the activation of TLR9 or TLR 7 depending on the time or stage of infection and alteration in the available ligand." (PMID 28400771, 2017). "A comparison between cytokine MFI at peak parasitaemia and baseline (day 0) showed that TLR9-stimulated pDC expressed more IFN-α at peak-infection, whilst TNF production remained unchanged." (PMID 28572564, 2017). "Rather, the benefit of S. Typhi more resembled the partial benefit seen in PD-fed mice receiving an intraperitoneal TLR9 agonist CpG-ODN 1668 at the time of infection." (PMID 27467505, 2016). "TLR9−∕− neutropenic mice exhibited a decreased inflammatory response compared to wild-type 2 days post infection, but was significantly increased 4 days post infection indicating an immunoregulatory role for TLR9 in A. fumigatus infection." (PMID 26973640, 2016). "TLR7/9-/- mice produce increased levels of IL6, TNF-α, and IL17A during Histoplasma infection, and similar results have been observed for the endemic fungal pathogen P. brasiliensis during infection of TLR9-/- mice." (PMID 27459510, 2016). "We have found that TLR2 and TLR4 cooperate in the early control of this infection, while TLR9 is dispensable." (PMID 28119856, 2016). "Possibly, the increased TLR9+CD11b+ PMNs and sTLR9+CD11b− PMNs present a rapid innate immune response of the PMNs to bacterial invasion at the early stage of infection." (PMID 27057095, 2016). "brucei parasites penetrate the BBB very early during infection (within 2–3 days post infection), whereby they proposed that TLR9 and MyD88-mediated activation of DCs triggers via type-I IFN (IFN-α/β) T-cell activation." (PMID 27446070, 2016).
infection (continued). "During infection bacterial DNA is released and exposes host cells that express TLR9 to the unmethylated CpG motifs, thus stimulating a protective immune response against the invading pathogen." (PMID 27716055, 2016). "Only TLR9 was significantly up regulated in the early stages of infection and marginal significance was revealed for FoxP3 when both Groups 1 and 2 were compared with controls." (PMID 26465878, 2015). "The relatively high CpG index of 17.7 found for T. pallidum indicates that TLR9 can be the primary inducer of the NF-κB pathway during infection with T. pallidum." (PMID 26179610, 2015). "Transcription of TLR3 and TLR9 was down regulated in the later stages of infection (comparing Groups 1 and 2)." (PMID 26465878, 2015). "In the reported study, we determined that GA heterozygotic status at TLR9 2848 SNP was associated with susceptibility of fetuses and newborns to congenital infection with HCMV and an increased—by 4.81 times—risk of the infection." (PMID 25844529, 2015). "Production of IFN-α in the context of infection by B. burgdorferi is, to a large part, dependent on TLR9 23 sensing unmethylated CpG motifs in microbial DNA." (PMID 26152778, 2015). "Transcription of TLR2 and TLR9, together with FoxP3, were all up regulated in the earlier stages of infection when compared with the controls." (PMID 26465878, 2015). "Toll-like receptor 9 (TLR9) has a key role in the recognition of pathogen DNA in the context of infection and cellular DNA that is released from damaged cells." (PMID 24610369, 2014). "A rapid increase of TNFα production was observed in TLR9-/- AMs compared to WT AMs, at both 2 and 4 hours post-infection." (PMID 24595157, 2014). "In pregnant nonobese diabetic (NOD) mice and wild-type (WT) mice in the same strain background, an infection was mimicked by toll-like receptor 9 (TLR9) activation through CpG1826-injection." (PMID 24714634, 2014). "In contrast, infection with strain 26695, virB4–, virD4–, or 8822 resulted in a significant increase in the expression of TLR9 6 h and 24 h after infection." (PMID 23755130, 2014). "The improvement of airways bacterial clearance resulted in the attenuation of the intensity of late pulmonary inflammation accompanied with reduced airways histological lesions in TLR9-/- mice, 24 h after the initiation of infection." (PMID 24595157, 2014). "The infection of human neutrophils with H. pylori resulted in a significant increase in the expression of TLR9, and this increase was observed with all the strains tested, regardless of the presence of cagPAI." (PMID 23755130, 2014). "At the early time point (3 hours) post-infection the same load of bacteria was found in WT and TLR9-/- mice lung." (PMID 24595157, 2014). "In the present study, we showed that infection by fully virulent B. anthracis spores induced not only transcriptional upregulation of tlr9 but also production of TNF-α in murine macrophage RAW264.7 cells." (PMID 25472474, 2014). "Three hours post-infection, a significant increase in KC, IL-1β, TNFα, and IL-6 levels was detected in BALs from TLR9-/- compared to WT mice." (PMID 24595157, 2014). "Despite a comparable clinical and intestinal (e.g. histopathological) outcome of infection we observed several TLR-9-mediated effects." (PMID 24932221, 2014). "In contrast, 17 hours post-infection with P. aeruginosa, different lesion profiles were identified between WT and TLR9-/- mice." (PMID 24595157, 2014). "A marked increase in the PMNs number was observed in BALs of WT and TLR9-/- mice at 24 hours after infection." (PMID 24595157, 2014). "Three hours post-infection, significantly higher numbers of AMs were found in BALs of both WT and TLR9-/- mice compared to PBS-treated mice." (PMID 24595157, 2014). "Infection of bovine monocytes with MAP resulted in a 10-fold increase in TLR9 expression, supportive of both the involvement of this receptor in promoting MAP clearance and the therapeutic potential of TLR9 agonists for JD." (PMID 26664912, 2014).
infection (continued). "Mammalian Toll-like receptors (TLRs) such as TLR9 initiate immune responses to infection by recognizing microbial nucleic acids." (PMID 24714634, 2014). "CpG-ODN bind to TLR9 expressed on APCs, natural killer cells and other lymphocytes, mediating anti-infection or antitumor immune response, which has attracted significant attention among immunological investigators." (PMID 24748977, 2014). "On the contrary, when infection is detected via TLR9 and RIG-I, the restriction is reversed and pro-inflammatory response of the macrophages is restored." (PMID 24409285, 2014). "In order to induce acute ileitis TLR-9-/- and wildtype (WT) mice were subjected to a peroral infection with 100 cysts of T. gondii ME49 strain." (PMID 24932221, 2014). "We report that TLR9-/- mice exhibit a significant resistance to lethal infection following pulmonary infection with P. aeruginosa compared to wild type (WT) mice." (PMID 24595157, 2014). "Given that dsDNA and RNA:DNA hybrids coexist alongside other nucleic acids during pathogen infection, the precise nature of the substrates sensed by TLR9 remains an open question and an interesting future challenge." (PMID 24514026, 2014). "In this study, we evaluated the contribution of TLR9 activation during the infection by P. brasiliensis using an experimental model of P. brasiliensis infection of wild-type and TLR9−/− mice." (PMID 23936560, 2013). "We found that the lack of this receptor results in tissue damage and increased expression of cytokines, culminating in a higher death rate of TLR9−/− mice early post infection." (PMID 23936560, 2013). "A possible cooperative role of both receptors during infection has been suggested in a study that evaluated the resistance to infection of TLR2/TLR9-double knockout (TLR2/TLR9−/−) mice." (PMID 23650544, 2013). "In contrast, TLR9 was committed to IL-12/IL-23p40 production by MHCII+CD11chigh cells that constitute the main source of IL-12/IL-23p40 during infection." (PMID 23650544, 2013). "For this purpose, we compared the capacity of F4/80+CD11b+ cells from WT and from Rec TLR9−/− mice to produce IL-12/IL-23p40 after CpG DNA stimulation during infection." (PMID 23650544, 2013). "We further show that TLR9 plays a protective role early after intravenous infection with P. brasiliensis, as infected TLR9−/− mice died at higher rate during the first 48 hours post infection than wild type mice." (PMID 23936560, 2013). "Our results show that TLR9 recognizes P. brasiliensis, playing a major regulatory role during early times of in vivo infection with its absence making the host more prone to increased liver pathology and premature death, mainly mediated by neutrophils." (PMID 23936560, 2013). "Given the in vitro impact of P. brasiliensis recognition by TLR9, we next sought to investigate a role for this receptor during the course of an in vivo experimental infection." (PMID 23936560, 2013). "As presented above, a decreased capacity of macrophage/monocyte lineage to respond to TLR9 agonist was observed during the acute phase of infection." (PMID 23650544, 2013). "Since a significantly higher recruitment of dendritic cells and neutrophils is observed upon infection of TLR9−/− hosts, it is possible that the higher cytokine expression observed in this scenario results from the fact that more producing cells are present." (PMID 23936560, 2013). "Toll-like receptor 4 was increased 18, 24, and 36 h after CASP (all versus control P = 0.0067, P = 0.0092, P = 0.0001), whereas TLR9 was elevated only 36 h after infection (versus control P = 0.0029)." (PMID 23935245, 2013). "The phenotype of TLR9−/− hosts observed during the early stages of P. brasiliensis infection was reverted upon a transient, 48 hours post-infection, neutrophil depletion." (PMID 23936560, 2013). "The importance of TLR9 signaling in polymicrobial infection has already been shown by others and by our group." (PMID 23690658, 2013).